INS (insulin)
Diseases named in the same sentence as INS in open-access papers (continued):
Sharing a sentence is not in itself a finding about the gene and the disease.
Obesity (continued). "Furthermore, different sensitivities to metabolic hormones and adipokines such as leptin and insulin, which interestingly are often altered as a result of the nutritional environment in early life, may underlie some of the sex differences in prevalence of type 2 diabetes and obesity." (PMID 29773464, 2018). "The impairment of insulin-evoked vasorelaxation by resistin may represent an important link between changes in adipokines and CVDs in obesity." (PMID 30416448, 2018). "Sequence analysis revealed a PPARγ response element within the chemerin (RARRES2) promoter; thus, insulin-sensitising drugs that activate PPARγ might be beneficial for the treatment of obesity and T2DM." (PMID 29848608, 2018). "In addition, obesity and those treated with larger insulin doses were found to have lower variability." (PMID 28755478, 2018). "Additionally, the adiponectin: leptin ratio has been shown to correlate with variations in systolic BP, insulin sensitivity, total cholesterol and low-density lipoprotein in MetS patients with obesity." (PMID 30114249, 2018). "People suffering from obesity who have reduced their body weight have improved their metabolic and inflammatory biomarkers and increased their sensitivity to insulin; however, very few studies have researched how community intervention on nutritional status can affect metabolic parameters." (PMID 29402762, 2018). "Other authors consider that adiponectin and omentin, especially when synthesized from subcutaneous adipose tissue, might be the most important adipokines in the regulating obesity, insulin sensitivity and T2DM." (PMID 30666216, 2018). "In obesity, this correlates with reduced activation of the proximal insulin cascade." (PMID 30183740, 2018). "In addition, hypothalamic inflammation leads to unbalanced leptin and insulin signaling, contributing to the development of obesity." (PMID 30037112, 2018). "Genome scans and association studies have linked LEPR to measures of adiposity including energy expenditure in: a population with elevated obesity levels, fat mass, skinfold and fat-free mass; BMI trends in childhood; and leptin levels, body composition, insulin dysregulation and glucose metabolism." (PMID 30121879, 2018). "Low GH action in obesity might also lead to metabolic alterations of other tissues such as the adipose tissue and skeletal muscle that might also contribute to deteriorated insulin sensitivity and glucose tolerance in obese patients with NASH." (PMID 30206761, 2018). "In this study, we aimed to elucidate the regulatory mechanism of GD improving glucose and lipid metabolism in an obesity animal model induced by high-fat and high-sugar diet in combination with low dose of streptozocin and an insulin-resistant HepG2 cell model induced by dexamethasone." (PMID 29599810, 2018). "Hence, mitoQ treatment of live mice subject to HF‐induced obesity results in changes at the islet level consistent with a reduced demand for insulin." (PMID 29864244, 2018). "In the same line of findings, it has been exposed that obesity and overnutrition-induced inflammation could promote hypothalamic ER stress, leading to insulin and leptin resistance and, ultimately to weight gain." (PMID 30018241, 2018). "Notably, in the non-diabetic obese group, the beneficial effect of exercise was mainly reflected in decreases in insulin and obesity indexes, whereas in the diabetic group, it was reflected in a significant reduction in HbA1c levels." (PMID 30579336, 2018). "Long-term consumption of pulses in other populations, who share metabolic abnormalities with women with PCOS, has been associated with positive metabolic effects such as lowering postprandial blood glucose and insulin concentrations, and decreasing hypercholesterolemia, blood pressure, and obesity." (PMID 30274344, 2018).
Obesity (continued). "Further, a growing body of literature exists in support of the hypothesis that maternal nutrition and obesity can affect offspring metabolic outcomes such as increased adiposity, insulin sensitivity, blood pressure, and non-alcoholic fatty liver disease." (PMID 29447203, 2018). "Further, S6K null mice are insulin-sensitive and resist diet-induced obesity." (PMID 30210580, 2018). "However, when individuals develop obesity owing to overconsumption of simple sugars, which per se stimulate insulin secretion (via incretins or directly), the hyperinsulinemia causes hypersecretion of pancreatic enzymes." (PMID 30293998, 2018). "In addition, ceramide 18:1/16:0 have also been identified as a key ceramide that negatively regulates insulin sensitivity and fatty acid oxidation in obesity." (PMID 29751643, 2018). "Moreover, as expected, we found that subjects with obesity and those with increased WC present higher IR and secretion and lower insulin sensitivity." (PMID 29791653, 2018). "Early work suggested that sub-acute chronic inflammation that typified diet related diseases including obesity, T2D and atherosclerosis disrupted metabolism, wherein cytokines impeded a range of metabolic pathways such as insulin signaling, and reverse cholesterol transport." (PMID 30304866, 2018). "Similarly, insulin, c-peptide of insulin, albumin, uric acid, and vitamin D were identified as main variables for predicting obesity." (PMID 29650030, 2018). "Overnutrition triggers excessive ectopic lipid accumulation, increases low-grade chronic inflammation and suppresses insulin signaling pathway, leading to the development of metabolic diseases such as obesity, insulin resistance, dyslipidemia and non-alcoholic fatty liver disease (NAFLD)." (PMID 30596786, 2018). "In this investigation, we test the central hypothesis that PDKs1-4 are a pharmacological target for lowering glucose levels and restoring insulin sensitivity in obesity and type 2 diabetes (T2D)." (PMID 29656110, 2018). "In sum, increasing the dietary amount of lard-based fat from 10 to 45% or 60% of the total energy intake leads to obesity accompanied by increased fasting blood glucose and insulin (pointing toward reduced insulin sensitivity), reduced glucose tolerance and increased plasma leptin." (PMID 30670942, 2018). "Reduced capillary density in skeletal muscle is observed in obesity and this can limit the diffusion of insulin, the oxidative capacity of muscle fibers, and the tyrosine kinase activity of the insulin receptor, with the latter associated with muscle fiber type." (PMID 30258366, 2018). "Interestingly, feeding standard low-fat minipig chow to Göttingen minipigs ad libitum (versus restrictively) led to obesity with lower fasting plasma glucose and insulin and higher insulin sensitivity." (PMID 29682581, 2018). "Among two mechanisms of the adipose tissue expansion, hypertrophy-dominant obesity (increase in cell size) is harmful due to pro-inflammatory cytokine release and impaired insulin sensitivity, but hyperplasia-dominant obesity (increase in cell number) is known to be beneficial." (PMID 30542326, 2018). "In this manner, levels of insulin are regulated commensurate to levels of food intake and if impaired may contribute to obesity-induced diabetes." (PMID 30532738, 2018). "Diet-induced obesity can lead to a shift in the activation state of adipose tissue macrophages from an M2-polarized state in lean animals to an M1 proinflammatory state that contributes to insulin resistance." (PMID 29545532, 2018). "Accordingly, we reasoned that sustained/elevated hypothalamic TCPTP levels in diet-induced obesity might shift POMC neural responses so that the majority of POMC neurons are unresponsive or inhibited by insulin." (PMID 30230471, 2018).
Obesity (continued). "Taking advantage of this, our purpose was to determine, in DIO mice, the isolated effect of exercise (without body weight modification) on insulin and leptin action on hypothalamus, on peripheral insulin sensitivity, and glucose homeostasis, all of which are negatively affected by obesity." (PMID 29371411, 2018). "Insulin levels rise and its sensitivity decreases with obesity." (PMID 29743077, 2018). "NIRKO mice have an elevated plasma insulin level, increased food consumption, and are susceptible to diet-induced obesity without alterations in brain development or neuronal survival." (PMID 30423881, 2018). "Maternal overweight/obesity and GDM are associated with adverse short- and long-term outcomes in the offspring, the latter identified to be related especially to increased birth weight, insulin and leptin." (PMID 29925339, 2018). "In addition to improved β-cell function, the same exercise intervention also improved insulin sensitivity with similar reductions in anthropomorphic measures in male adolescents with obesity." (PMID 29471797, 2018). "Indeed, the stimulation of proteasomal activity by exogenously expressing Nrf1 in BAT improved systemic insulin sensitivity and glucose homeostasis in genetic and dietary obesity mouse model." (PMID 29538286, 2018). "We demonstrate that mice lacking the CDK6 protein or its kinase domain (K43M) exhibit significant increases beige cell formation, enhanced energy expenditure, better glucose tolerance, and improved insulin sensitivity, and are more resistant to high-fat diet-induced obesity." (PMID 29523786, 2018). "A more debated hypothesis positions the physiological components of obesity, including glucose, insulin, and leptin signaling as key contributors to the etiology of OSA." (PMID 30127766, 2018). "Vaspin is an adipokine which improves glucose metabolism and insulin sensitivity in obesity." (PMID 28932870, 2018). "Poor biological rhythms may influence hormone metabolism, such as leptin, insulin, and cortisol, leading to obesity." (PMID 30103464, 2018). "MicroRNAs are also involved in the regulation of insulin signaling and blood glucose levels in T2D, and participate in lipid metabolism, adipogenesis, and adipocyte differentiation in obesity, with specific microRNA signatures involved in the pathogenesis of each disease." (PMID 30445764, 2018). "However, endogenous NPs contribute to the control of glucose homeostasis under conditions of pathological diet-induced obesity by improving β-cell proliferation and function in early stages of enhanced insulin demand." (PMID 30016962, 2018). "Indeed, elevated intake of diets containing high amounts of saturated fatty acids induces obesity and its major complications including inflammation, insulin resistance, and ectopic lipid deposition, among others." (PMID 30116154, 2018). "However, because certain Clostridiaceae family members also positively correlate with obesity and other metabolic perturbations, in our study it is difficult to link Clostridiaceae specifically to increased insulin secretion." (PMID 29502266, 2018). "Concomitantly, obesity, metabolic syndrome and during prediabetes insulin promotes lipogenesis, triglyceridemia and hepatic steatosis and further in the presence of high glucose milieu, insulin actively promotes liver glycogen synthesis and de novo lipogenesis was in accordance with our data." (PMID 30451881, 2018). "A chronic, low-grade, “sterile” inflammation is present in obesity, and pro-inflammatory mediators including cytokines and ROS/RNS cause insulin resistance in peripheral insulin sensitive tissues and lead to dysfunction and apoptosis of insulin-producing β-cells in pancreatic islets." (PMID 29426925, 2018). "Furthermore, OXT nasal spray treatment in obese patients effectively reversed obesity and related lipid disorders and improved blood glucose and insulin postprandial levels." (PMID 29867762, 2018).
Obesity (continued). "Obesity and compensatory excessive circulatory insulin trigger low tissue sensitivity to insulin." (PMID 29805204, 2018). "Obesity promotes deregulated production of adipokines and a high flux of free fattyacids in the circulation through the mechanism of lipolysis, demonstrating theestablishment of a vicious cycle with insulin resistance." (PMID 29791596, 2018). "Since the introduction of intensified insulin therapy in order to optimize glycemic control and to reduce microvascular complications, the prevalence of obesity, other features of the metabolic syndrome and cardiovascular complications have increased dramatically." (PMID 28588898, 2017). "As 84% of EC is Type I endometrioid adenocarcinoma, which has a stronger association with obesity than does non-endometrioid Type 2 EC, obesity with its concomitant increased estradiol and insulin levels, remains a risk factor for EC." (PMID 28698465, 2017). "These factors, which are reduced in obesity models, may exert a direct action on beta-cell function and/or insulin sensitivity." (PMID 28827671, 2017). "Thus, the perivisceral obesity leads to a decrease in peripheral sensitivity to insulin, especially in patients with reduced glycemic control." (PMID 28468307, 2017). "Thus, in several insulin-resistant states, such as obesity, T2DM and in patients with coronary artery disease adiponectin plasma levels are reported to be reduced." (PMID 28695134, 2017). "Patients with T2DM carrying the Pro12Ala polymorphism have higher risk of obesity than non-carriers although the same energy intake, perhaps secondary to a better insulin sensitivity." (PMID 27894098, 2017). "Because 8 did not decrease the size of adipocytes but did up-regulate the secretion of adiponectin, 8 may induce anti-obesity effects by improving the insulin resistance of adipocytes." (PMID 28441735, 2017). "Gene expression studies on hNAG-18 have shown that GDF-15 may influence age-associated pathology development through mechanisms related to obesity, appetite, insulin sensitivity, energy metabolism and mTOR activity." (PMID 27734214, 2017). "Accumulating evidence indicates that obesity contributes to down-regulation of insulin secretion, defecting insulin action or both, which may disturb carbohydrate and lipid homeostasis." (PMID 29036927, 2017). "Fetuin-A could have different effects in women, in those with lower degrees of obesity, or on hepatic insulin sensitivity specifically." (PMID 28770230, 2017). "Mixed responses in insulin AUC were observed among male and female participants with overweight and obesity following an 8-week intervention involving five cups of yellow peas, chickpeas, navy beans, and lentils per week in comparison to dietary counselling for energy restriction." (PMID 28976933, 2017). "Obesity leads to high circulating concentrations of insulin, leptin and insulin-like growth factor-I (IGF-I) and low levels of adiponectin, which have been described to promote prostate cancer growth and progression, thus increasing the risk of advanced prostate cancer." (PMID 29228634, 2017). "Other pro-obesity related factors such as plasma insulin and leptin were significantly improved, suggesting that in addition to its lipase inhibitory effects; MLE60 positively modulates adipocytic mechanisms through a leptin like activity, to exhibit anti-obesity properties." (PMID 28814950, 2017). "Adipose tissue HIF1A activity is influenced by multiple signals, including adipogenesis, insulin, hypoxia, and obesity, but the induction of HIF1A by E2 can induce VEGFA and thereafter promote angiogenesis, a process that is required for adipocyte differentiation and adipose tissue growth." (PMID 29196658, 2017). "Inhibition of PI3K also prevents the manifestation of IR within these tissues, supporting the hypothesis that lipid metabolites play an integral role in the manifestation of IR in obesity and is secondary to increased insulin signaling and HI." (PMID 28466412, 2017).
Obesity (continued). "Similarly, NR supplementation attenuated HFD-induced obesity in mice, improved insulin sensitivity and glucose tolerance, and ameliorated the adverse lipid profile." (PMID 29264533, 2017). "Obesity-related factors such as inflammation, elevated levels of insulin and insulin-like growth factors, or other carcinogens may play different roles on postmenopausal and premenopausal breast cancer risk." (PMID 29216920, 2017). "One primary reason for it here would be the smaller sample size, while it could be possibly affected by individual variation in impaired level of glucose tolerance due to resistance or impaired secretion of insulin with age or obesity." (PMID 28381223, 2017). "Interestingly, obesity courses with the dysfunction of key regulatory systems, including GH, insulin and IGF1 axes, which are crucial for the correct development and maintenance of several organs 29, including the PG." (PMID 28244645, 2017). "In conclusion, the PLIN1 gene is epigenetically regulated and promoter methylation is inversely correlated with basal lipolysis in women suggesting that epigenetic regulation of PLIN1 is important for increased adipocyte lipolysis in insulin resistant states such as obesity." (PMID 28860604, 2017). "It is possible to modify negative risk factors such as obesity, dyslipidemia, and hypertension, as well as factors involved in systemic inflammation, insulin sensitivity, oxidative stress, endothelial function, thrombosis, and cardiac rhythm." (PMID 28671637, 2017). "Auricular stimulation may be involved in several mechanisms of BW regulation and obesity such as anorexigenic and orexigenic peptides, glucose metabolism, insulin resistance, lipid metabolism, and inflammatory markers." (PMID 29358964, 2017). "Taken together, we hypothesized that MnP would be effective in inhibiting obesity-induced NF-κB driven inflammation in the livers of obese mice, thus maintaining glucose homeostasis and promoting insulin sensitivity, while diminishing NAFLD." (PMID 29104232, 2017). "In addition to its effects on inflammation, TNFα has detrimental effects on insulin sensitivity, and a TNFα knockout mouse is protected against obesity-induced glucose intolerance and hyperinsulinemia." (PMID 28646079, 2017). "Several studies have earlier demonstrated that feeding of male Wistar rats with high sucrose did not induce obesity through reduced energy expenditure but was shown to cause impairment of insulin action and elevation of plasma triglycerides." (PMID 28831087, 2017). "In addition, GLP-1 analogue liraglutide exhibited anti-obesity effects via enhancing peripheral insulin sensitivity." (PMID 29245916, 2017). "However, emerging evidence support the concept of endothelial regulation of metabolism, e.g., through endothelial interactions with the insulin targets in obesity." (PMID 28848738, 2017). "In this study, cinnamon polyphenol increased PPARα and IRS expression in the liver; this may have potential insulin sensitizing effect and may increase IR in a rat obesity model." (PMID 28396714, 2017). "In contrast, n-3 has been reported to prevent obesity and improve insulin sensitivity." (PMID 29036761, 2017). "In addition, obesity is associated with the development of T2DM and GDM due to the increased peripheral resistance to insulin." (PMID 28386562, 2017). "It seems that the reason for this considerably high insulin sensitivity is subcutaneous fat–dominant obesity with reduced visceral fat, higher plasma ghrelin and adiponectin levels, reduced β-cell response to glucose stimulation, and insufficient growth hormone." (PMID 28854950, 2017). "Thus, activation of resolution programming through enhanced expression of SPM receptors by myeloid cells provides a rationale for gain-of-function studies to limit inflammation and improve insulin sensitivity in diet induced obesity and insulin resistance." (PMID 28993702, 2017).